GPRC5A (G protein-coupled receptor class C group 5 member A)
Diseases named in the same sentence as GPRC5A in open-access papers (continued):
Sharing a sentence is not in itself a finding about the gene and the disease.
pancreatic cancer (27 papers, 2014 to 2025). "GPRC5A is also an under-recognized pancreatic cancer-associated gene and showed high expression levels in multiple cancers." (PMID 36358856, 2022). "Furthermore, the influence of GPRC5A on promoting the proliferation and migration of pancreatic cancer cells was partially reversed by YAP1 deficiency in PANC1 cells, which was verified by CCK-8, colony formation, transwell, and wound healing assays." (PMID 36735162, 2023). "Further, more detailed information about IMUP and GPRC5A including their physicochemical properties, their association with immune cells infiltration, the mutation ratio, copy number variation and methylation ratio in pancreatic cancer were analyzed." (PMID 34819098, 2021). "Another study proved that knocking out GPRC5A suppressed the resistance to gemcitabine in a pancreatic cancer cell line (MIA PaCa-2), and its over-expression enhanced the resistance of ovarian cancer cells." (PMID 40362181, 2025). "Recent studies have shown that GPRC5A (G-Protein coupled Receptor Class C, Group 5, Member A) functions in the progression of a variety of cancer, including pancreatic cancer." (PMID 36735162, 2023). "In our experiments, GPRC5A was markably increased in pancreatic cancer compared to normal or adjacent tissue, and we first confirmed that in pancreatic cancer, GPRC5A interference inhibited tumor growth in nude mice." (PMID 36735162, 2023). "In this study, we demonstrated that crosstalk between the Hippo pathway and GPRC5A-cAMP-CREB signaling was critical for pancreatic cancer progression." (PMID 36735162, 2023). "In summary, our findings demonstrated that inhibiting YAP1 was beneficial in disrupting the adverse effects of GPRC5A on pancreatic cancer cells." (PMID 36735162, 2023). "The results showed that GPRC5A positively regulated YAP1, CYR61, cyclin D1, c-Myc and CTGF expression at the transcriptional level, as evidenced by overexpression and knockdown of GPRC5A in pancreatic cancer cells." (PMID 36735162, 2023). "Taken together, our data indicate that GPRC5A knockdown suppresses pancreatic cancer cell proliferation and migration in vitro." (PMID 36735162, 2023). "We first examined GPRC5A expression in pancreatic cancer cell lines and normal cells at the protein and mRNA levels, and observed that GPRC5A expression was higher in pancreatic cancer cells than in normal cells." (PMID 36735162, 2023). "GPRC5A was significantly upregulated in pancreatic cancer compared to normal tissues analyzed through the TCGA and GEPIA databases." (PMID 36735162, 2023). "We propose that the GPRC5A-cAMP-CREB axis is a crucial pathway in the promotion of pancreatic cancer progression." (PMID 36735162, 2023). "Our experiments demonstrated that disrupting YAP1 expression almost completely inhibited the effect of GPRC5A on pancreatic cancer cells." (PMID 36735162, 2023). "In this study, we first address the roles of GPRC5A in nude mice and show that its overexpression in pancreatic cancer is predictive of poor prognosis." (PMID 36735162, 2023). "In pancreatic cancer, GPRC5A can indirectly interact with the RNA-binding protein HuR, which influences its translation." (PMID 36735162, 2023). "To further demonstrate the role of GPRC5A in pancreatic cancer, we detected its expression in pancreatic cancer cells and tissues." (PMID 36735162, 2023). "GPRC5A expression was increased in pancreatic cancer, and disruption of GPRC5A expression inhibited tumor growth in vivo." (PMID 36735162, 2023). "This study unveiled molecular mechanism of miR-135b-5p/KLF4/GPRC5A axis in human pancreatic cancer cells and demonstrated the probability of miR-135b-5p as a new therapeutic target." (PMID 35027543, 2022). "In conclusion, this study provided significant insights into the miR-135b-5p/KLF4/GPRC5A axis in pancreatic cancer progression." (PMID 35027543, 2022). "In summary, we validated the impact of miR-135b-5p/KLF4/GPRC5A regulatory axis on pancreatic cancer cells." (PMID 35027543, 2022).
pancreatic cancer (continued). "Above all, this research attempted to clarify molecular mechanism whereby miR-135b-5p regulates KLF4/GPRC5A to affect malignant progression of pancreatic cancer cells." (PMID 35027543, 2022). "GPRC5A is expressed as an oncogene in various cancers, and its oncogenic role in pancreatic cancer has also been validated." (PMID 36358856, 2022). "After exhibiting that GPRC5A mRNA levels hold the second highest average expression among different cancer types in pancreatic cancer, they examined and compared its expression levels in normal pancreatic tissues, primary PDAs and metastatic tumors." (PMID 34572861, 2021). "Consistently, knockdown of RAI3 in pancreatic cancer cells led to decreased proliferation and reduced migration, indicating a pro-metastatic role for GPRC5A in pancreatic cancer." (PMID 32719397, 2020). "The standard chemotherapy treatment with gemcitabine increased the expression of GPRC5A by the interaction between its mRNA and RNA-binding protein HuR; whereas, knockout of GPRC5A sensitized pancreatic cancers to gemcitabine chemotherapy." (PMID 31540286, 2019). "For instance, GPRC5A, a member of the G protein-coupled receptor family, is shown upregulated in pancreatic cancer primary and metastatic lesions as compared with normal tissues, and it promotes the growth and migration of pancreatic cancer cells." (PMID 31540286, 2019). "For example, GPR161 is functionally expressed in breast cancer and GPRC5A in pancreatic cancer and GPR68 in the tumor microenvironment." (PMID 32039239, 2019). "Immunocytochemistry staining of pancreatic cancer cells supports the mRNA expression data, indicating the presence of GPRC5A protein in these cells." (PMID 29872392, 2018). "In pancreatic cancer, suppression of GPRC5A was found to increase the cell sensitivity to multiple chemotherapeutic drugs, including gemcitabine, oxaliplatin, and fluorouracil." (PMID 30417009, 2018). "Suppression of GPRC5a results in decreased cell growth, proliferation and migration in pancreatic cancer cell lines via a STAT3 modulated pathway, independent from ERK activation." (PMID 28114355, 2017). "In summary, we presented evidence that suggests that GPRC5A participates in a complex set of interactions in the pancreatic cancer context." (PMID 27415424, 2016). "On the other hand, when we knocked down GPRC5A we sensitized pancreatic cancer cells to gemcitabine." (PMID 27415424, 2016). "Experimentation with two more pancreatic cancer cell lines (Panc-1, PL-5) showed similar improvements in their gemcitabine sensitivity following GPRC5A knockdown." (PMID 27415424, 2016). "In this report, we present evidence that in multiple pancreatic cancer cell lines the levels of GPRC5A mRNA and protein are higher compared with the normal pancreatic epithelial cell line hTERT-HPNE." (PMID 27415424, 2016). "Conversely, when we inhibit GPRC5A in pancreatic cancer cell lines such as MIA PaCa-2, Panc-1 and Capan-2 and in normal pancreatic cell line such as hTERT-HPNE we decrease the cells' ability to form colonies and we hinder migration." (PMID 27415424, 2016). "In vitro studies of multiple pancreatic cancer cell lines showed that an increase in GPRC5A protein levels promoted pancreatic cancer cell growth and migration." (PMID 27415424, 2016). "We examined both GPRC5A mRNA and protein expression levels in six pancreatic cancer cell lines and in the normal pancreatic epithelial cell line hTERT-HPNE that is derived from the pancreas duct." (PMID 27415424, 2016). "The level of GPRC5A mRNA in the six pancreatic cancer cell lines is statistically significantly higher compared with hTERT-HPNE." (PMID 27415424, 2016). "Further work is warranted before it can be established unequivocally that GPRC5A is an oncogene in the pancreatic cancer context." (PMID 27415424, 2016). "We also show that in actual pancreatic tumor samples GPRC5A protein levels were dramatically higher than in normal pancreatic ductal cells." (PMID 27415424, 2016).
pancreatic cancer (continued). "Unexpectedly, when we treated pancreatic cancer cell lines with gemcitabine (2′,2′-difluorodeoxycytidine), we observed an increase in GPRC5A protein abundance." (PMID 27415424, 2016). "Through a series of experiments with multiple pancreatic cancer cell lines, we examine the impact of GPRC5A overexpression on cell growth, colony formation ability and migration." (PMID 27415424, 2016). "Knockout of GPRC5A (G protein-coupled receptor family C, group 5, member A) reduced the proliferation and migration ability of pancreatic cancer cell lines and suppressed the resistance of pancreatic cancer cell lines to the chemotherapy drugs gemcitabine, oxaliplatin and fluorouracil." (PMID 40362181, 2025). "Moreover, in vitro experiments also confirmed that GPRC5A expression promotes proliferation, migration and invasion of pancreatic cancer cells." (PMID 38634049, 2024). "Additionally, our research reveals a strong correlation between high GPRC5A expression in pancreatic cancer tissues and elevated levels of CD20+ B cell infiltration (rs = 0.5711, p < 0.0001)." (PMID 38634049, 2024). "Interestingly, our results reveal that, in contrast to KRT7, the expression of YWHAZ and GPRC5A genes demonstrates a relatively stronger correlation with B cell infiltration in pancreatic cancer." (PMID 38634049, 2024). "A xenograft model of pancreatic cancer was established to explore the role of GPRC5A in vivo." (PMID 36735162, 2023). "In addition, we observed increased GPRC5A expression in the tumor tissues in contrast to normal tissues in pancreatic cancer patients by IHC." (PMID 36735162, 2023). "miR-135b-5p is an oncogene that negatively regulates KLF4 expression by direct binding to its 3′UTR region, resulting in reduced levels of KLF4 and activation of G protein-coupled receptor class C group 5-member A (GPRC5A), and promoting the malignant progression of pancreatic cancer." (PMID 37239940, 2023). "Interestingly, GPRC5A knockdown also markedly decreased the migration ability of pancreatic cancer cells." (PMID 36735162, 2023). "Therefore, it is still important to determine the key downstream molecules of GPRC5A and its mechanism of action in pancreatic cancer." (PMID 36735162, 2023). "Similarly, the GPRC5A protein level was higher in pancreatic cancer tissues than in adjacent normal tissues." (PMID 36735162, 2023). "GPRC5A interacts with the Hippo pathway to promote the progression of pancreatic cancer." (PMID 36735162, 2023). "Furthermore, our data showed that silencing YAP1 by siRNA disrupted the malignant biological behavior of GPRC5A in pancreatic cancer cells." (PMID 36735162, 2023). "Then, we performed functional experiments to assess the role of GPRC5A in pancreatic cancer cells." (PMID 36735162, 2023). "HTFtarget database was employed for prediction of downstream regulatory genes of KLF4, and notably upregulated 35 genes in microarray GSE22780 were then intersected with the predicted genes, and the most obvious difference in pancreatic cancer was found in the expression of GPRC5A." (PMID 35027543, 2022). "Our results stressed that KLF4, as a vital target of miR-135b-5p, could influence promoter region of GPRC5A, thus affecting the malignant progression of pancreatic cancer." (PMID 35027543, 2022). "Both in vivo and in vitro experiments verified that miR-135b-5p could affect malignant progression of pancreatic cancer through KLF4/GPRC5A." (PMID 35027543, 2022). "However, GPRC5A frequently expresses oncogenic characteristics in other cancers such as colon, gastric, liver, breast and pancreatic cancers." (PMID 33788883, 2021). "Moreover, some contradictory views exist about the prognostic effect of GPRC5A in various cancers, including breast cancer, pancreatic cancer, and hepatocellular cancer." (PMID 33788883, 2021).
pancreatic cancer (continued). "Lastly, local IHC experiment performed on PAAD tissue array which was produced with 62 local hospital patients samples confirmed that GPRC5A and IMUP were abnormally up-regulated in pancreatic cancer, which directly associated with worse patients both overall (OS) and recurrence free survival (RFS)." (PMID 34819098, 2021). "Dysregulation of GPRC5A expression has been observed in other human cancers, such as breast cancer, colorectal cancer, gastric cancer, hepatocellular carcinoma, pancreatic cancer, prostate cancer and ovarian cancer." (PMID 33788883, 2021). "Furthermore, our data provide a molecular basis to explain GPRC5A overexpression previously observed in solid tumours, such as pancreatic cancers." (PMID 30143543, 2018). "Moreover, the basic expression levels of GPRC5a in pancreatic cancer tissues at different stages were analyzed with the TCGA (The Cancer Genome Atlas) dataset." (PMID 29949874, 2018). "Knockdown of GPRC5A with siRNAs leads to morphological changes in pancreatic tumor cells AsPc-1." (PMID 30417009, 2018). "GPRC5A (RAI3), coding for a seven transmembrane G protein-coupled receptor is known to be overexpressed in pancreatic cancer and might be an interesting candidate for therapeutic intervention." (PMID 28114355, 2017). "Additionally, we are able to establish GPRC5A's participation in the pancreatic cancer cells' response to gemcitabine treatment." (PMID 27415424, 2016). "Gemcitabine treatment could induce apoptosis in pancreatic cancer cells that was enhanced when we inhibited GPRC5A with an siRNA." (PMID 27415424, 2016). "Further studies of GPRC5A are warranted as it could prove to be a new candidate target for developing an alternative strategy for treating pancreatic cancer." (PMID 27415424, 2016). "In the pancreatic cancer context, very little is known about GPRC5A." (PMID 27415424, 2016). "By analyzing messenger RNA (mRNA) expression data from 675 human cancer cell lines and 10 609 samples from The Cancer Genome Atlas (TCGA) we found that GPRC5A's abundance in pancreatic cancer is highest (cell lines) or second highest (TCGA) among all tissues and cancer types." (PMID 27415424, 2016). "In this report, we provide evidence that supports the hypothesis that GPRC5A acts as an oncogene in the pancreatic cancer context." (PMID 27415424, 2016). "Subsequent reports indicated that in breast cancer, colorectal cancer and pancreatic cancer GPRC5A could also behave as an oncogene." (PMID 25621293, 2014). "Thus, we investigated cAMP expression after regulating GPRC5A in pancreatic cancer cells." (PMID 36735162, 2023). "Moreover, we show that the proliferation and migration induced by GPRC5A in pancreatic cancer could be rescued by inhibiting YAP1 expression." (PMID 36735162, 2023). "Therefore, we tried to excavate the genes which are regulated by KLF4 in pancreatic cancer, finding that the promoter region of GPRC5A could be regulated by KLF4." (PMID 35027543, 2022). "Therefore, we believe that GPRC5A may be affected by KLF4 in pancreatic cancer and thus take an essential regulatory part." (PMID 35027543, 2022). "This disclosed that miR-135b-5p could modulate GPRC5A in pancreatic cancer cells by targeting KLF4." (PMID 35027543, 2022). "GPRC5a, which encodes the G-Protein-Coupled Receptor family C, member 5, group A, also named retinoic acid-inducible 3 (RAI3), is overexpressed in a variety of cancers, including pancreas cancer, which makes it a potential biomarker for early diagnosis of cancer." (PMID 33117331, 2020). "Functional analysis of GPRC5a in different carcinomas indicated that RAI3 has pleiotropic effects and might confer resistance to Gemcitabine in pancreatic cancer, however the ligand of GPRC5a remains elusive, but GPRC5a overexpression might lead to a reduction of EGFR levels." (PMID 28114355, 2017). "In addition, our results showed that inhibition of GPRC5A could also sensitize pancreatic cancer cells to Trichostatin A." (PMID 27415424, 2016).
pancreatic cancer (continued). "Moreover, when we inhibited GPRC5A in the pancreatic cancer cell lines Panc-1 and Capan-2 we could inhibit the cells' migration ability." (PMID 27415424, 2016). "The results showed that GPRC5A was closely correlated with CYR61, cyclin D1, c-Myc, and CTGF in pancreatic cancer." (PMID 36735162, 2023). "We first found a significantly positive relationship between GPRC5A and YAP1 in pancreatic cancer using the GEPIA database." (PMID 36735162, 2023). "To explore the impact of GPRC5A on YAP1, we evaluated the relationship between GPRC5A and YAP1 downstream target genes in pancreatic cancer patients." (PMID 36735162, 2023). "Next, we examined YAP1 expression in pancreatic cancer cell lines and normal cells at both the mRNA and protein levels and found that the expression of YAP1 was positively related to GPRC5A expression." (PMID 36735162, 2023). "GJB3, TMPRRS4, GPRC5A, and TRIM29 were all identified previously, as upregulated in pancreatic cancer tissues." (PMID 37779898, 2023). "The protein expression levels of MYEOV, GPRC5A, and KRAS showed a consistent trend in pancreatic cancer tissues and normal tissues adjacent to pancreatic cancer from three pancreatic cancer patients." (PMID 36358856, 2022). "As such, our results indicated that GPRC5A was upregulated in pancreatic cancer, and upregulated expression of KLF4 also inhibited the expression of GPRC5A." (PMID 35027543, 2022). "MiR-135b-5p fostered malignant behaviors of pancreatic cancer cells by decreasing KLF4, while KLF4 hampered the disease by negatively modulating the transcriptional expression of GPRC5A." (PMID 35027543, 2022). "To better investigate how MYEOV, GPRC5A, and KRAS act together in pancreatic cancer, we utilized the String database, a dedicated database for studying protein interaction networks." (PMID 36358856, 2022). "Through a multiplex analysis approach, we explored that MYEOV has a positively correlated expression relationship with GPRC5A and KRAS, and further developed a molecular network of pancreatic cancer-related genes centered on MYEOV." (PMID 36358856, 2022). "We analyzed mRNA expression levels of MYEOV, GPRC5A, KRAS, EGFR, SERPINB5, EIF4G2, and PDCD4 in pancreatic cancer tissues and normal tissues adjacent to pancreatic cancer from three pancreatic cancer patients." (PMID 36358856, 2022). "We also validated the role of ceRNA network genes such as GPRC5A, SERPINB5, KRAS, EGFR, EIF4G2, and PDCD4 in pancreatic cancer." (PMID 36358856, 2022). "It was found that MYEOV, GPRC5A, SERPINB5, KRAS, EGFR, and EIF4G2 were all significantly elevated in pancreatic cancer tissues, and the expression trends of GPRC5A, SERPINB5, KRAS, EGFR, and EIF4G2 in different stages were nearly identical." (PMID 36358856, 2022). "These interactions of GPRC5A with HuR, gemcitabine and the other chemotherapeutic agents imply a potential pro-oncogenic role for this gene; therefore, targeting of these interactions could augment the death rate of pancreatic cancer cells post-chemotherapy treatment." (PMID 34572861, 2021). "In pancreatic cancer however, knockdown of RAI3 (the gene for GPRC5A) led to decreased proliferation and reduced migration, indicating a pro-metastatic role for GPRC5A in pancreatic cancer." (PMID 32719397, 2020). "The immortalized human ductal pancreatic epithelial (HDPE) cell line showed only negligible expression of RAI3 protein or GPRC5A mRNA expression, whereas pancreatic cancer lines displayed highly variable but detectable over-expression." (PMID 28114355, 2017). "Interestingly, most of the relationships between drug resistance and the expression levels of the up-UDEGs ANLN, GPRC5A and SERPINB5 were positive, indicating that these three genes are closely related to the resistance mechanisms of pancreatic cancer." (PMID 40362181, 2025).